TFRC (transferrin receptor)
Diseases named in the same sentence as TFRC in open-access papers (continued):
Sharing a sentence is not in itself a finding about the gene and the disease.
glioma (93 papers, 2011 to 2025). A benign or malignant brain and spinal cord tumor that arises from glial cells (astrocytes, oligodendrocytes, ependymal cells). "Transferrin receptor (TfR)-targeted liposomes offer greater specificity, enabling more precise drug delivery to glioma cells expressing TfR and reducing drug distribution to normal tissues." (PMID 40723232, 2025). "We present the synthesis and characterization of the T7 peptide (HAIYPRH) as a targeting ligand for the transferrin receptor, which is highly expressed on both the blood-brain barrier and glioma cells." (PMID 40574045, 2025). "This study aimed to develop a chimeric element-regulated ferritin heavy chain 1 (FTH1) reporter system to enhance MRI-based glioma detection while enabling targeted therapy via transferrin receptor (TfR)-mediated drug delivery." (PMID 40723232, 2025). "The biological evaluation of the design attributes of the synthesized targeted conjugate focused on in vitro studies using U87MG, a malignant glioma cell line that inherently overexpresses the transferrin receptor (TfR)." (PMID 40574045, 2025). "Here, we show that this nanocarrier, named The-0504, can cross the BBB and specifically deliver the payload to gliomas that express high amounts of the ferritin/transferrin receptor TfR1 (CD71)." (PMID 38615026, 2024). "All‐atom docking studies demonstrated that flubendazole bound closely with xCT, and TFRC, validating its role in inducing glioma ferroptosis via modulation of these proteins." (PMID 39543084, 2024). "Specifically, we use the expression of Ki67 as a marker of proliferating cells and CD71, or transferrin receptor 1, as a previously established marker of stem-like properties in glioma cells." (PMID 35906273, 2022). "The micelle was expected to be quickly absorbed into glioma cells with the transferrin (Tf)-targeting molecule on the surface layer, where the transferrin receptor (TfR) is greatly overexpressed relative to the normal cells." (PMID 35903366, 2022). "D-T7 was used for targeting glioma as it has high affinity for transferrin receptor (TfR), overexpressed on endothelial and brain capillary glioma cells." (PMID 36678688, 2022). "Transferrin receptor 1 (TfR1) controls the rate of iron uptake by glioma cells by regulating the amount of iron delivered to cells to meet metabolic requirements." (PMID 36072803, 2022). "The TFRC expression was higher in glioma, and the progression and oncogenicity of glioma were regulated by hsa-miR-144-3p/TFRC signaling." (PMID 35359663, 2022). "As transferrin receptor (TfR) is over-expressed by the brain capillary endothelial (hCMEC/D3) and glioma cells, a mouse monoclonal antibody, RI7217, with high affinity and selectivity for TfR, was used to study the brain targeted drug delivery system." (PMID 32292496, 2020). "Apoferritin (APO), an endogenous nanosize spherical protein, can specifically bind to brain endothelial cells and glioma cells via interacting with the transferrin receptor 1 (TfR1)." (PMID 29726297, 2018). "The transferrin receptor (TfR) is expressed on all normal tissue cells, but it is chosen as an immunotherapy target for gliomas and other tumor cells because of the high iron requirement of rapidly proliferating neoplasms." (PMID 22069735, 2011). "By analyzing the oscillations of clock-related genes (BMAL1 and PER2) and transferrin receptor levels in U87 glioma cells, we identified optimal timing for the complexes’ cellular uptake and payload delivery using two complementary computational tools (CircWave and CosinorPy)." (PMID 40649908, 2025). "Additionally, glioma cells can upregulate the expression of transferrin receptor 1 (TfR1) and ferritin, which are involved in iron uptake and storage, respectively." (PMID 38020609, 2023). "The transferrin receptor targeting ligand has the ability to cross the blood-brain barrier, which is currently the main obstacle to the treatment of many brain diseases including glioma." (PMID 37919282, 2023).
glioma (continued). "Finally, immunohistochemical experiments and single-cell analysis confirmed the expression of TFRC in glioma." (PMID 36483569, 2022). "More importantly, for the classification of tumors of the central nervous system (WHO CNS5), patients with isocitrate dehydrogenase (IDH) wildtype have a higher expression level of TFRC than those with isocitrate dehydrogenase (IDH) mutations and chromosomal 1p/19q codeletions (P < 0.00)." (PMID 36483569, 2022). "Moreover, transferrin receptor (TfR) has been extensively researched as a target for gliomas, because TfR is over-expressed on glioma cells." (PMID 33790740, 2021). "TFRC may be a potential prognostic biomarker and an immunotherapeutic target for glioma." (PMID 36483569, 2022). "Therefore, our study supports that TFRC is a potential target for glioma therapy." (PMID 25356585, 2014). "This system integrated transferrin receptors (TF-R) and cell-penetrating peptides (CPP), promoting efficient drug delivery to gliomas." (PMID 39911386, 2025). "Hydrogen peroxide (H2O2) can activate transferrin receptor (TFR) and lead to iron overload, which induces cell death in glioma." (PMID 40822852, 2025). "Transferrin receptor 1 (TfR1) is highly expressed in brain capillary endothelial cells and TMZ-resistant glioma cells." (PMID 38443927, 2024). "In our study, we observed an increase in TFRC expression and a decrease in FTH1 expression in gliomas following orexin‐A treatment." (PMID 38685674, 2024). "To verify the expression pattern of TFRC in LGG, we analyzed the Oncomine database and found that there was also a higher TFRC expression level in different kinds of glioma than in the normal group." (PMID 36483569, 2022). "T7 is a seven-peptide ligand of transferrin receptors (TfR) capable of circumventing the BBB and then targeting glioma." (PMID 28687044, 2017). "The LDA results revealed a significantly increased expression of iron metabolism-related genes ferritin heavy chain 1 (FTH1), transferrin receptor (TFRC), and Acyl-CoA synthetase long-chain family member 4 (ACSL4), while GPX4 expression was decreased in the glioma samples compared to the controls." (PMID 41154694, 2025). "Interestingly, our data validated that the expression of TFRC and DMT1 was upregulated and FHC downregulated in glioma cells after flubendazole treatment." (PMID 39543084, 2024). "It is known that the expression of transferrin receptors (TfR) in glioma cells is significantly higher compared to non-tumor cells, which enables the targeting of the resulting nanocarrier." (PMID 37896182, 2023). "Some researchers have reported that pathobiological events, most notably mTORC1 hyperactivity, which can be related to high-grade glioma, can increase Fe(III) uptake into cancer cells by regulating the activity of the transferrin receptor (TfR) in preclinical models." (PMID 35407338, 2022). "Gliomas highly express transferrin receptor and albumin-binding receptor SPARC, while M2 TAMs also highly express SPARC and mannose, therefore facilitating the dual-targeting role of these nanoparticles for both gliomas and M2 TAMs." (PMID 33790906, 2021). "Transferrin receptors (TfR) has been observed to express on both the BBB and glioma cells." (PMID 30394123, 2018). "The targeting transferrin receptor nanoparticles display an inherent capacity for a highly therapeutic approach in targeting glioma stem cells and non-stem cells tumors." (PMID 29088799, 2017). "In this study, a peptide targeting the transferrin receptor (T7 sequence: HAIYPRH) was employed as the carrier to leverage the high expression of transferrin on the blood-brain barrier (BBB) and its overexpression on glioma cells for site-specific drug delivery." (PMID 40574045, 2025). "Notably, transferrin receptor (TfR)-targeted NPs, including T7-functionalized PLGA NPs, achieve approximately sixfold increases in brain delivery, with measurable improvements in therapeutic outcomes in stroke and glioma models." (PMID 41012505, 2025).
glioma (continued). "Consequently, orexin‐A may induce ferroptosis in gliomas by selectively targeting NFE2L2 and regulating the downstream expression of GPX4, TFRC and FTH1." (PMID 38685674, 2024). "A recent study showed that RBCMs can successfully target the transferrin receptor at the blood-brain barrier and glioma surface, as well as CD13 that is highly expressed by tumor cells, through the dual modification of T7 peptide and polypeptide NGR, and significantly enhance the anti-glioma effect." (PMID 37128288, 2023). "Transferrin receptor (TFR) is overexpressed in many types of cancers, such as liver cancer 75, kidney cance 76, glioma 77, and pancreatic cancer 78, compared to non-tumor tissues, which makes it a promising target for cancer therapy." (PMID 39744692, 2025).
hepatocellular carcinoma (67 papers, 2009 to 2025). A malignant tumor that arises from hepatocytes. "Several previous studies have successfully inhibited the proliferation and invasion of various tumor cells, such as glioblastoma, lymphoma, ovarian cancer, and hepatocellular carcinoma cells, by inhibiting the TFRC gene." (PMID 40510157, 2025). "Studies have shown that TFRC is highly expressed in a variety of tumors, including breast cancer, glioma, ovarian cancer, lung cancer, hepatocellular carcinoma, and colon cancer, and is considered a universal cancer marker." (PMID 40510157, 2025). "O-GlcNAcylation of TFRC regulates ferroptosis in hepatocellular carcinoma by enhancing TFRC stability and promoting iron accumulation through decreased MARCH8-mediated ubiquitination." (PMID 39315094, 2024). "A study on hepatocellular carcinoma reported that intracellular degradation of TFRC impeded the sensitivity of tumor cells to ferroptosis." (PMID 38221933, 2024). "Whereas TfR is highly expressed in hepatocellular cancer cells and blood vessels after trauma and induces OS and iron accumulation, causing ferroptosis, and the knockdown of TfRC ameliorates ferroptosis." (PMID 39596528, 2024). "CHIP acts as an oncogene in hepatocellular carcinoma by promoting cell proliferation and inhibiting ferroptosis through the degradation of transferrin receptor 1 (TfR1)." (PMID 39315094, 2024). "Classic experiments conducted 40 years ago gave an exquisite account of the kinetics of the internalization of transferrin and the transferrin receptor in a human hepatoma cell line 47,48." (PMID 37286800, 2023). "In human hepatocellular carcinoma tissues, miRNA-152 levels are reduced, and transferrin receptor 1 (TFR1) is overexpressed." (PMID 37046995, 2023). "Hepatitis C virus also utilizes TFRC for entry in human hepatocytes, and knockdown of TFRC inhibits hepatitis C virus infection in human hepatoma cells." (PMID 35821227, 2022). "The Fe3O4@ZnO nanocomposites functionalized with transferrin receptor antibody (TfR Ab) delivered DOX into hepatocellular carcinoma SMMC-7721 cells, resulting in G2/M cell cycle arrest in combination with irradiation." (PMID 32168899, 2020). "MiR-320 and miR-152 target iron uptake related gene transferrin receptor 1 (TFR1) and inhibit cell proliferation in lung adenocarcinoma A549 cells and hepatocellular carcinoma, respectively." (PMID 31554201, 2019). "The results of cellular uptake revealed that Tf-BMs-DOX recognized hepatocellular carcinoma HepG2 cells more specifically compared to HL-7702 normal hepatocytes because of high expression of transferrin receptor (TfR) on the surface of HepG2 cells." (PMID 31423412, 2019). "HNF4α has been shown to control iron homeostasis in liver and hepatoma cells through the regulation of transferrin, transferrin receptor-1 and hepcidin genes." (PMID 31532389, 2019). "Surprisingly, three host proteins were thus purified from human hepatoma and colon cancer cell lines: transferrin receptor 1 (TFR1), heat shock protein 90 (HSP90), and Na+/K+ ATPase or Mg++ ATPase." (PMID 27802297, 2016). "Some studies have discovered that TFRC controls malignant behavior and stemness of tumor stem cells in hepatocellular carcinoma by regulating iron accumulation, which may improve therapeutic approaches." (PMID 35372510, 2022). "Similarly, serum levels for soluble transferrin receptor (sTfR) in patients with hepatoma and haematologic malignancies are significantly increased as compared with those of normal controls." (PMID 23192001, 2012). "In hepatocellular carcinoma (HCC), O-GlcNAcylation can increase ferroptosis sensitivity via transcriptional elevation of TFRC to increase the iron concentration in cells." (PMID 37675227, 2023). "Altogether, these results provided evidence that USP22 promotes the proliferation of hepatocellular carcinoma cells by stabilising CKD11B and increases Sorafenib resistance through reducing H2BK120ub level and TFRC transcription in vivo." (PMID 40341781, 2025).
hepatocellular carcinoma (continued). "In hepatocellular carcinoma (HCC), tumor cells exhibit increased expression of ACSL4 and transferrin receptor 1 (TfR1), as well as decreased GPX4 activity." (PMID 40733290, 2025). "USP22 promotes the proliferation of hepatocellular carcinoma cells by stabilising CDK11B and enhances resistance to Sorafenib by inhibiting ferroptosis through the USP22/H2BK120ub/TFRC axis." (PMID 40341781, 2025). "The TFRC gene, coding for CD71, belongs to a tumor Treg signature common to several cancers, including hepatocellular carcinoma (HCC)." (PMID 38954474, 2024). "ACO1, also known as IRP1, is an RNA-binding protein that controls iron homeostasis by regulating TFRC and FTH1 expression in CCA and hepatocellular carcinoma." (PMID 36733386, 2022). "USP22 promotes the proliferation of hepatocellular carcinoma cells via deubiquitinating and stabilising cyclin‐dependent kinase CDK11B, and it inhibits Sorafenib‐induced ferroptosis by decreasing H2BK120ub occupancy at TFRC TSS downstream region." (PMID 40341781, 2025). "In hepatocellular carcinoma (HCC), one of the most significant breakthroughs in exemplifying O-GlcNAcylation–ferroptosis interactions came from Zhou and colleagues’ discovery that TFRC undergoes O-GlcNAcylation, which plays a role in erastin-induced ferroptosis sensitivity." (PMID 41008983, 2025). "In addition, for the first time, LASS2 overexpression was found to further inhibit cancer cell invasion and migration by regulating the ferroptosis signalling pathway in thyroid, breast, and hepatocellular cancer cells, possibly through direct interactions between LASS2 and TFRC." (PMID 38419028, 2024). "Transferrin receptor 1 (TFRC 1), which mediates the virus entry, its overexpression is observed in hepatocellular carcinoma (HCC)." (PMID 35216324, 2022). "Additionally, USP22 downregulates transferrin receptor (TFRC) transcription by removing H2B lysine 120 ubiquitination (H2BK120ub) from TFRC transcription start site (TSS) downstream region, thereby inhibiting Sorafenib‐induced ferroptosis in hepatocellular carcinoma." (PMID 40341781, 2025). "Over-expression of transferrin receptor 1 (TFRC) is observed in hepatocellular carcinoma (HCC); however, there is a lack of conclusive information regarding the mechanisms of this dysregulation." (PMID 26657500, 2016).
malaria (61 papers, 2005 to 2025). Malaria is a serious and sometimes fatal disease caused by a parasite that commonly infects a certain type of mosquito which feeds on humans. "Ferritin, transferrin saturation, hepcidin, and soluble transferrin receptor levels were associated with malaria-specific antibody levels." (PMID 32507899, 2021). "Elevated soluble transferrin receptor concentration (>8.3 mg/L) was associated with younger age, malaria, greater mean reticulocyte counts, inflammation, HbSS genotype, and ID." (PMID 28671630, 2017). "Studies have shown that host cells influence the role of iron in regulating malaria immune responses through transferrin receptor 1 (TFR1), affecting both pathogen control and host adaptive immunity." (PMID 41422632, 2025). "More recent reports of associations between other markers of iron stores (transferrin saturation, soluble transferrin receptor [sTFR]/log10 ferritin ratios) and malaria in pregnant women and children support the notion of a true biological effect." (PMID 35619134, 2022). "Cellular Fe import, via the transferrin receptor 1 (TFR1/CD71), supports TH type 1 (TH1) cell immunity and its regulation by induced Treg (iTreg) cells as well as antibody responses to vaccination and immunity against infection by pathogens such as Plasmodium, the causative agent of malaria." (PMID 38499786, 2024). "Erythroid progenitor suppression in malaria has been ascribed to the increased free haemoglobin and hemozoin containing monocytes in the bone marrow and a shift of the transferrin receptor expression from erythroid to non-erythroid cell to increase immunological response to blood-stage parasite." (PMID 27618936, 2016).